LDHB (lactate dehydrogenase B)
Diseases named in the same sentence as LDHB in open-access papers (continued):
Sharing a sentence is not in itself a finding about the gene and the disease.
tumor (continued). "However, the exact roles of LDHB in HCC progression in vivo, and whether LDHB suppresses HCC progression by affecting the tumor immune environment is unclear." (PMID 38739169, 2024). "Expression of MCT4 and combined LDH (LDHA and LDHB) in the tumour epithelium are important in determining clinically significant intermediate-risk disease, while MCT1 expression may also play a role in more aggressive tumours." (PMID 35075123, 2022). "In addition, LDHB silencing reduced tumor initiation and growth of xenograft tumors." (PMID 35877003, 2022). "Our microscopic analysis revealed that LDHB expression in the xenografts was highly heterogeneous, confirming that lactate-mediated metabolic symbiosis might occur not only between cancer cells but also between all cell types within a tumor." (PMID 35877003, 2022). "Notably, LDHA was found to be expressed mainly in the central hypoxic area of the tumor, colocalized with carbonic anhydrase IX (CAIX or CA9), and some cells invading the corpus callosum (CC), while LDHB was prevalently expressed in peripheral tumor areas and cells invading the CC." (PMID 36278433, 2022). "The increased LDHB promoted more pyruvate comfort to lactic acid, and the increased lactate levels in the tumor microenvironment could promote tumor invasion and metastasis through the activation of vascular growth factor, and promotion the expression activity of hyaluronan with its receptor CD44." (PMID 35978348, 2022). "Thus, it was reasonable to believe that knockdown LDHB could inhibit tumour growth and induce differentiation, which were essential for ATPR‐treated AML." (PMID 32391634, 2020). "In addition, LDHB has been demonstrated to be a key regulatory element of lactate catabolism in oxygenated subpopulations of tumor cells, known as oxidative cancer cells, which prefer to utilize lactate to fuel oxidative metabolism in order to spare glucose for anaerobic, glycolytic tumor cells." (PMID 33050176, 2020). "In addition, increased LDHA and decreased LDHB expressions facilitate tumor formation and progression through remodeling of the tumor microenvironment, increasing proliferation, and inducing epithelial-to-mesenchymal transition, cell migration and invasion, and angiogenesis." (PMID 31932876, 2020). "Therefore, LDHB upregulation may indicate chemoresistance, and upregulating of glycolysis and OXPHOS may be associated with metabolic alterations in tumor cells in response to chemotherapy." (PMID 33170151, 2020). "Recent reports suggest a novel, alternate hypothesis on metabolism in tumor cells, where hypoxic and glucose-deprived cells depend upon LDHB to utilize lactate secreted from the adjacent cells, which are undergoing aerobic glycolysis, in a phenomenon called “reverse Warburg effect”47,49." (PMID 31558821, 2019). "Spatial transcriptomics data from HCCDB further demonstrated that LDHA expression levels were significantly higher than LDHB within HCC cells, while LDHB was predominantly expressed in immune cells of the tumour microenvironment." (PMID 41454479, 2026). "By contrast, in inflamed or tumor microenvironments where extracellular lactate is abundant, uptake via MCT1 leads to conversion of lactate to pyruvate by LDHB, a reaction that generates NADH and lowers the intracellular NAD+/NADH ratio." (PMID 40710349, 2025). "Lactate uptake by oxidative tumor cells occurs primarily through monocarboxylate transporter 1 (MCT1), after which LDHB converts lactate into pyruvate, fueling oxidative metabolism." (PMID 40733189, 2025). "Regulatory T cells (Tregs): Tumor-infiltrating Tregs express high levels of MCT1, which enables lactate uptake and conversion via lactate dehydrogenase-B (LDHB) to support oxidative metabolism." (PMID 40710349, 2025). "Volcano plot analysis of differentially expressed genes showed that NDRG1 is markedly upregulated in tumor tissues, alongside several key metabolic genes, including LDHA, SLC16A1, PKM, HK1, and LDHB." (PMID 40539245, 2025).
tumor (continued). "Understanding the interplay among CCDC80, LDHA and LDHB could provide insights into the metabolic reprogramming of cancer cells and identify novel targets for therapeutic intervention aimed at restoring normal metabolic processes and enhancing anti-tumor immunity." (PMID 39308689, 2024). "An association of an impaired LDH activity and a reduced stress response has been confirmed in tumor cells with a genetic knockout of LDHA and LDHB." (PMID 38229111, 2024). "The peptides with increased presentation in SK-Mel-28 dr cells derived from EIF4B, FAM20B, LDHB, CYCS, C5orf22, RCAN1 and DIEXF and were recurrently identified in TvHdb in a variety of tumor patients." (PMID 39835134, 2024). "The results demonstrated that LY2874455 (an FGF inhibitor) treatment notably suppressed tumor growth, improved the survival rate, and reduced the LDHA/LDHB ratio and serum lactate concentration." (PMID 38764020, 2024). "Each of these genes controls key steps in regulating metabolic homeostasis, and their expression is dysregulated in tumour cells and HCC, with LDHA typically upregulated and LDHB downregulated." (PMID 38710924, 2024). "The relationship to immune infiltration of LDHA and LDHB genes was further investigated using tumor immune estimation resource 2 (TIMER2) and Tumor-Immune System Interactions and DrugBank (TISIDB) databases, respectively." (PMID 37547725, 2023). "We also performed IHC analysis of SW480 xenograft tumor tissues and confirmed that the protein levels of the glycolytic enzymes GLUT1, GLUT4, HK2, LDHA and LDHB were lower in xenografts from PROX1 knockdown cells than in those from control cells." (PMID 36594098, 2023). "We explored the expression levels of four major lactate dehydrogenase (LDHA, LDHB, LDHC, and LDHD) and found that LDHA was significantly higher expressed in tumor tissue-derived cells and LDHB was higher expressed in normal tissue-derived cells." (PMID 37795453, 2023). "Validation using Western blotting analysis on 13 patients with type I EC at tumour stage 1 and 13 endometria samples confirmed the altered abundance of HBB, CKB, LDHB, and HSPB1." (PMID 37569364, 2023). "The LDHA, LDHB, LDHL, and hicD genes are involved in this pathway and exchange metabolic fuel with the tumor stroma, making them promising targets for CRC chemotherapeutic drugs." (PMID 37998446, 2023). "Among them, LDHA and LDHB are the significant components of LDH, which mediate the metabolic plasticity of tumor cells." (PMID 37547725, 2023). "In the current study, we detected LDHA and LDHB expression using public databases and WB analyses, explored their prognostic role in ccRCC using TMA, then revealed the tumor-immune interaction of LDHA/LDHB in ccRCC using TIMER2 and TISIDB databases." (PMID 37547725, 2023). "Due to the lower expression in most glycolytic tumor cells and metabolic organs like the liver and muscle than LDHA, LDHB escaped the attention of researchers for a long period." (PMID 36407005, 2022). "Invasive tumor spheroids from P3 stem‐like cells were included in paraffin and LDHA and LDHB expressions were analyzed in coronal sections." (PMID 36278433, 2022). "ACSL3, EPAS1, FASN, GSTP1, LDHB, and NEDD4L were identified as the candidate genes through the intersection of tumor-related genes, DEGs, and ferroptosis-related genes." (PMID 35223835, 2022). "Tumor sections were then stained for the MΦ marker CD163 and LDHB using the PhenOptics multispectral imaging system." (PMID 34158867, 2021). "In GBM, HK2 has been shown to be a key mediator of aerobic glycolysis and tumor growth, which is in line with our observed expression ratio of LDHA/LDHB in the IDH wild-type enriched patient cluster." (PMID 33532725, 2021). "For instance, luminal A tumours generally exhibit decreased lactate secretion, characterized by high levels of monocarboxylate transporter 1 (MCT1) and lactate dehydrogenase B (LDHB)." (PMID 34572926, 2021).
tumor (continued). "LDH is a key metabolic enzyme that degrades pyruvate into lactate; LDH comprises the LDHA and LDHB subunits, and increased expression of LDHA promotes glycolysis and tumor growth." (PMID 33723221, 2021). "Genes related to oxidative phosphorylation and those related with chemoresistance and poor prognosis such as HNRNPA0, HDAC1, LDHB, AREG, and PSCA were upregulated in subgroups of brain metastasis-derived tumor cells in chemotherapy treated patients." (PMID 33170151, 2020). "IHC analyses of tumor tissues revealed that the expression of Ki67, MCT1 in tumor cells and LDHB in CAFs was enhanced in cancer cells when ITGB2 was overexpressed in CAFs." (PMID 33204328, 2020). "Collectively, these in vivo and in vitro results indicated the K329 deacetylation of LDHB by SIRT5 promoted cancer cell proliferation and tumour growth." (PMID 30443978, 2019). "Deacetylated LDHB increases the autophagy of tumor cells, helps lysosomal acidification and autolysosomal maturation, while silencing or the inhibition of SIRT5 leads to LDHB acetylation at K329, which inhibits its proautophagic activity." (PMID 31035592, 2019). "Ribosomal protein S7 (RPS7) inhibits tumor growth by controlling glycolysis via suppressed expression of HIF-1α and LDHB." (PMID 31146503, 2019). "We investigated the profiles for six protein markers, FGFR1, FRS2, S6K1, LDHB, MYPT1, and P-LDHA, in tumor-adjacent stroma." (PMID 31316912, 2019). "In the present study, LSCC demonstrated higher LDHB expression than RSCC, implicating that the left and right side of the colon differ in their tumor metabolic activity, particularly with regard to anaerobic glucose metabolism." (PMID 24137329, 2013). "To elucidate the role played by ERRα in the glycolytic adaptation of tumor cells, we focused on the regulation of lactate dehydrogenases A and B (LDHA, LDHB) and the LDHA/LDHB ratio." (PMID 23516535, 2013). "LDHB, which was detected in BTCC urine samples of BTCC, is reported to be correlated with tumor expansion and invasion and patients with malignancies combined with increased serum LD isoenzymes activity usually have a poor prognosis." (PMID 21496341, 2011). "However, LDHB is markedly downregulated in KIRC, suggesting a potential tumor‐suppressive role in this context." (PMID 40977852, 2025). "Consistent with our in vitro findings, compared to control tumors, LDHB inhibition notably reduced tumor growth over time without evident side effects, i.e., the body weight of the animals did not decrease during the experiment." (PMID 40790017, 2025). "Additionally, lactate upregulates LDHB and MCT-1, converting lactate to pyruvate and generating ATP via the TCA cycle and oxidative phosphorylation (OxPhos), thereby driving tumor growth." (PMID 40416986, 2025). "The tumor cell line LS174T was used in the xenograft tumor mouse model because a radiosensitizing effect by diclofenac could be demonstrated for this cell line in vitro, and because a LDHA and LDHB gene knockout resulted in an increased radiosensitivity." (PMID 38229111, 2024). "We also observed that promoters of LDHB in tumor tissues were highly methylated compared to the normal tissues in the TCGA database and GSE10141 dataset." (PMID 38739169, 2024). "Phosphorylated LDHB instead converts pyruvate to lactate, which efficiently promotes NAD+ regeneration, glycolytic flux, lactate production, and biosynthesis with glycolytic intermediates, which facilitate tumor progression." (PMID 39334449, 2024). "Based on the Spearman correlation analysis in GEPIA, we identified a significant correlation between STAT1 and LDHA/LDHB/FGF1/FGF2 in tumor tissues but not in normal tissues." (PMID 38764020, 2024). "Notably, glycolysis enzymes (GPI, LDHA, LDHB, TPI1, and ALDOA) showed specific enrichment in exosomes from the primary tumor." (PMID 38419074, 2024).
tumor (continued). "We found several molecules that are significant in tumor initiation and treatment by immune checkpoint analysis, such as lymphocyte-activation gene 3 (LAG3), PTPRC, HAVCR2, B2M, LDHA, and LDHB, which may be used as a reference for tumor immunotherapy." (PMID 39014082, 2024). "Downregulating the expression of LDHA, LDHB, and MCT inhibits the production and influx/efflux of lactate in cancer cells, promoting the repolarization of macrophages from the tumor‐supportive M2 phenotype to the tumor‐suppressive M1 phenotype." (PMID 39415848, 2024). "LAGs like SLC16A8, SLC16A1, and LDHB have a higher methylation ratio in tumor tissue than in normal tissue; a lower methylation ratio of SLC16A7 and SLC16A3 is noticed in that comparison." (PMID 37122693, 2023). "In addition to LDHB, LDHA, as a component of LDH, also plays an important role in tumor proliferation." (PMID 37582735, 2023). "LDHB converts lactate to pyruvate and produces NADPH, thus providing sufficient energy for tumor cell proliferation while avoiding the accumulation of lactate, which indicates it could be the potential therapeutic target for ccRCC, especially metastatic ccRCC." (PMID 37547725, 2023). "Aurora-A can phosphorylate lactate dehydrogenase B (LDHB) on S162 to relieve substrate inhibition by pyruvate and enhance the latter's conversion into lactate, regenerating NAD+ and driving glycolytic flux required for biosynthesis and tumour progression." (PMID 37414143, 2023). "Supporting the glycolytic phenotype in more aggressive tumors with poor prognosis, higher expressions of lactate dehydrogenase B (LDHB) and lactate transporters (MCT1 and MCT4) and the inhibition of lactate secretion into the microenvironment to suppress tumor growth have been reported." (PMID 37685021, 2023). "Intriguingly, although Rho 0 cancer cells retained their proliferation ability, they completely lost their tumor initiation capacity, thus resembling cancer cells adapted to long-term LDHB silencing, e.g., A549 shLDHB clones (data not shown)." (PMID 35877003, 2022). "MRI-derived tumour [1-13C]lactate labelling correlated with epithelial mRNA expression of the enzyme lactate dehydrogenase (LDHA and LDHB combined), and the ratio of lactate transporter expression between the epithelial and stromal compartments (epithelium-to-stroma MCT4)." (PMID 35075123, 2022). "As ROS stabilizes hypoxia-inducible factor-1 alpha (HIF-1α) and promotes tumor progression, we determined if LDHA or LDHB knockout, which reduces oxidative stress, could also reduce HIF-1α protein level in tumors." (PMID 34176927, 2021). "Changes in the expression of LDHB and PDH were observed in tumor tissues as in CRC cells." (PMID 33806179, 2021). "We detected increased LDHA expression (p < 0.001) and reduced LDHB expression (p < 0.001) in tumor samples compared with non-tumoral adjacent tissue samples, suggesting that lactate production would be favored." (PMID 34208670, 2021). "We also observed a negative correlation between miR-375 and LDHB in tumor sections with Pearson's r = -0.7350 and p < 0.001." (PMID 34158867, 2021). "Live metabolic flux assays as well as transcript analysis of glycolytic enzymes revealed that LDHB suppression via miR-375 increased aerobic glycolysis in tumor cells and TAMs, without changing OCR." (PMID 34158867, 2021). "This differential metabolism was linked to increased centrally localized staining of glucose transporter 1 (GLUT1), lactate dehydrogenase B, monocarboxylate transporter 1 and cyclooxygenase 5B in HPV-positive tumours compared with more peripheral staining in HPV-negative tumours." (PMID 34696321, 2021). "Our study indicated that in tumor xenograft models, LDHA and LDHB knockout both significantly decreased the oxidative stress in the tumors scored by the biomarkers 4-HNE and protein carbonylation, indicating that LDH’s pro-oxidative activity is higher than its antioxidative activity in tumors." (PMID 34176927, 2021).
tumor (continued). "Unlike LDHA, the expression level of LDHB varies among different tumor cell types, and its role appears more complex." (PMID 33792181, 2021). "Moreover, among the different isoenzymes of LDH, two of them—LDHB and LDHA—were reported as deregulated proteins in cancer cells and are involved in the regulation of tumor–stroma nutrient exchange." (PMID 33802597, 2021). "First, elevated sLDH is not attributable to increased expression of LDHA and LDHB by tumor cells, nor does it reflect increased cellular proliferation or death." (PMID 33016647, 2020). "Considering the side effects of lysosomotropic agent chloroquine and a decrease in chloroquine activity by tumour acidity, SIRT5‐mediated LDHB deacetylation pathway might be a new therapeutic target for treating CRC." (PMID 30443978, 2019). "LDHA and LDHB, two isoenzymes of LDH, participate in tumor stroma metabolic interaction and exchange of metabolic fuel and thus could serve as potential anticancer drug targets." (PMID 31146503, 2019). "In contrast, in hepatocellular carcinomas, significantly low levels of LDHB compared to non-transformed tissues is observed, which predicts an unfavorable survival outcome in patients with this type of tumor." (PMID 31035592, 2019). "On the long list of factors that regulate tumor cell death, LDHA and LDHB are mentioned." (PMID 31035592, 2019). "Nearly all of these mutations resulted in amino acid changes in well-known metabolic genes such as LDHB (which is important in glycolysis for the conversion of lactate and pyruvate), TRIT1, which has been proposed as a tumour suppressor and CPT1C, important in fatty acid metabolism." (PMID 28163917, 2017). "Moreover, the expression level of the LDHB protein in HCC was correlated with pathological grade (P = 0.037), vascular invasion (P = 0.037), lymph node metastasis (P = 0.016), and tumor-node metastasis (TNM) stage (P = 0.007)." (PMID 26426634, 2015). "Our findings suggest that ERRα may influence tumor aggressiveness by metabolic modification and modulation of the LDHA/LDHB expression ratio." (PMID 23516535, 2013). "We evaluated the expression of LDHA (P00338) and B (P07195) in tumor tissue by qRT-PCR with specific primers for LDHA and B as well as by 2 western blots: one with an antibody recognizing LDHA and B, and one specific for LDHB." (PMID 22859959, 2012). "Additionally, CCDC80's positive correlation with LDHA and negative correlation with LDHB, although weak, implies its involvement in lactate metabolism, potentially influencing the tumor microenvironment and cancer cell metabolism." (PMID 39308689, 2024). "After the knockout of both LDHA and LDHB, aerobic glycolysis was disrupted, tumor growth was delayed but not abolished, and glucose metabolism was transformed to oxidative phosphorylation, indicating that tumor metabolism is a complex and flexible process and the Warburg effect is not irreplaceable." (PMID 37576895, 2023). "While various studies have revealed that the suppression of LDHA gene expression cripples tumor cell proliferation both in vitro and in vivo, it has also been suggested that the complete inhibition of the tumor growth can only be achieved through simultaneous disruption of both LDHA and LDHB genes." (PMID 37868977, 2023). "However, although both LDHB and GLDC expression levels varied significantly between tumor regions." (PMID 35877003, 2022). "In conclusion, our study shows for the first time that LDHB is essential for the maintenance of mitochondrial metabolism, especially nucleotide metabolism, demonstrating that LDHB is crucial for the survival and proliferation of NSCLC tumor-initiating cells and tumorigenesis." (PMID 35877003, 2022).